MRPS5 (mitochondrial ribosomal protein S5)
Synonyms: MRP-S5; S5mt; uS5m
Tractability: Small molecule: a structure with a bound ligand is known. PROTAC: ubiquitination databases record sites on it; its protein half-life has been measured.
Gene: Protein-coding gene on chromosome 2 (95,085,369 to 95,122,006, reverse strand). Ensembl gene ENSG00000144029.
Subcellular location: Mitochondrion
Subcellular location (Human Protein Atlas): Mitochondria; Midbody; Primary cilium
Pathways (Reactome):
Metabolism of proteins: Mitochondrial ribosome-associated quality control; Mitochondrial translation elongation; Mitochondrial translation initiation; Mitochondrial translation termination
Gene Ontology:
Molecular function: RNA binding; structural constituent of ribosome
Biological process: mitochondrial translation; translation
Cellular component: mitochondrial small ribosomal subunit; mitochondrion; mitochondrial inner membrane; ribosome
Genetic constraint (gnomAD): Loss-of-function variants: 30 observed, 49.07 expected, observed/expected ratio (o/e) 0.61, 90% interval 0.46 to 0.83. The upper end of that interval is the gene's LOEUF score, 0.83, which puts it in group 3 of 6, group 1 being the genes least tolerant of losing a copy. Missense variants: 522 observed, 508.47 expected, observed/expected ratio (o/e) 1.03, 90% interval 0.95 to 1.1. Synonymous variants: 182 observed, 184.2 expected, observed/expected ratio (o/e) 0.99, 90% interval 0.88 to 1.12.
Homologues: Orthologues: chimpanzee MRPS5 (99% identical), macaque ZNF514 (86% identical), dog MRPS5 (85% identical), rabbit MRPS5 (83% identical), pig MRPS5 (83% identical), guinea pig MRPS5 (82% identical), rat Mrps5 (81% identical), mouse Mrps5 (80% identical), tropical clawed frog mrps5 (61% identical), zebrafish mrps5 (54% identical), Drosophila melanogaster mRpS5 (33% identical), Caenorhabditis elegans mrps-5 (29% identical). Paralogues in human: RPS2 (18% identical).
Diseases named in the same sentence as MRPS5 in open-access papers:
MRPS5 is named in the same sentence as 23 diseases in open-access papers, as found by Europe PMC text mining. Sharing a sentence is not in itself a finding about the gene and the disease. The quoted sentences say what the papers report.
liver cancer (5 papers, 2021 to 2022). An epithelial or non-epithelial malignant neoplasm that arises from the liver. "MRPS5 deficiency significantly reduced the NAD+/NADH ratio and ROS production in liver cancer stem cells." (PMID 34440674, 2021). "Activation of the UPRmt in MRPS5 knockdown liver cancer stem cells increased mitochondrial membrane potential and reduced the oxygen consumption rate." (PMID 34440674, 2021). "In clinical samples, the expression of MRPS5 in liver cancer tissue was higher than in adjacent normal tissue." (PMID 34440674, 2021). "This study also indicated that deacetylated MRPS5 promotes the mitochondrial function of liver cancer stem cells and that acetylated MRPS5 translocation to the nucleus is necessary to promote glycolysis in liver cancer cells." (PMID 34440674, 2021). "It is known that mitochondrial ribosomal protein S5 (MRPS5) enhances the metabolic flexibility of liver cancer stem cells; however, the role of other mitochondrial ribosomal proteins in cancer pathogenesis remains unclear." (PMID 35242040, 2022). "In addition, MRPS5 enhances the metabolic flexibility of liver cancer stem cells." (PMID 34772924, 2021). "Deacetylated MRPS5 accumulates in mitochondria, promotes MPT, complex I activation, and production of NAD+, and is critical for maintaining stem-like features in liver cancer cells." (PMID 34885140, 2021).
Anxiety (3 papers, 2018 to 2022). Intense feelings of nervousness, tension, or panic often arise in response to interpersonal stresses. "Homozygous knock-in mutant mice carrying the mouse homologous Mrps5 V338Y mutation showed impaired mitochondrial function in the brain, decreased neurological stress tolerance, anxiety-related behavioral alterations and accelerated metabolic aging in muscle." (PMID 35457201, 2022). "Homozygous knock‐in mutant Mrps5 V338Y mice show impaired mitochondrial function and a phenotype composed of enhanced susceptibility to noise‐induced hearing damage and anxiety‐related behavioral alterations." (PMID 30237157, 2018). "Rather, as also supported by the results of our tests on anxiety and exploration, water‐maze performance was probably disrupted by an excessive sensitivity of Mrps5 mutants to the aversive stress conditions associated with this test." (PMID 30237157, 2018). "Furthermore, a V338Y mutation in another mitoribosomal protein, MRPS5, required for translational fidelity, that led to increased mitochondrial mistranslation had adverse effects, causing enhanced anxiety and susceptibility to noise‐induced hearing loss." (PMID 34096683, 2021). "In particular, MRPS5 V338Y mice exhibited increased anxiety-related behavioral changes and impaired learning under stressful conditions." (PMID 35457201, 2022).
myocardial infarction (3 papers, 2023 to 2025). Gross necrosis of the myocardium, as a result of interruption of the blood supply to the area, as in coronary thrombosis. "Intriguingly, deleting a single allele of mitochondrial small ribosomal subunit protein 5 (Mrps5) in mice enhances cardiomyocyte proliferation and cardiac regeneration in a surgical myocardial infarction mouse model." (PMID 40869184, 2025). "Remarkably, reducing Mrps5 and deleting Cpt1b not only led to hyperplastic hearts, but these mutations also promoted cardiac regeneration after myocardial infarction (MI) and ischemic-reperfusion injury, respectively." (PMID 38291287, 2024). "Interestingly, Mrps5 level was not significantly altered in the heart one month after myocardial infarction (MI); however, its expression was dramatically reduced in the heart six months after MI." (PMID 36949106, 2023).
cardiac hypertrophy (2 papers, 2023 to 2024). "We demonstrate that loss of Mrps5 in the developing heart leads to cardiac defects and embryonic lethality while postnatal loss induces cardiac hypertrophy and heart failure." (PMID 36949106, 2023). "Mrps5 deficiency links the mitochondrial cristae defect to abnormal cardiac development, pathological cardiac hypertrophy, and heart failure." (PMID 36949106, 2023). "We show that cardiac-specific loss of Mrps5 in adult mouse causes severe pathological cardiac hypertrophy and heart failure, and cardiac-specific loss of Mrps5 in mouse embryos causes abnormal heart development and embryonic lethality." (PMID 36949106, 2023). "Loss of Mrps5 in the heart results in cardiac hypertrophy, exhibiting as overt enlargement of the heart itself and increased heart weight to body weight ratio." (PMID 36949106, 2023). "Given that loss of Mrps5 resulted in cardiac hypertrophy and increased L-phenylalanine, we tested whether tetrahydrobiopterin (BH4) treatment could suppress hypertrophy in cardiomyocytes." (PMID 36949106, 2023). "In this study, we report a critical role for Mrps5 in heart development, pathological cardiac hypertrophy, cardiac metabolism, and mitonuclear communication." (PMID 36949106, 2023). "Encouraged by the findings that overexpression of Klf15 in neonatal Mrps5cKO mice was sufficient to prevent the development of cardiac hypertrophy, we explored the potential for Klf15 in the treatment of cardiac defects in adult Mrps5 mutant mice." (PMID 36949106, 2023). "The identification of Mrps5 as a marker of pathological cardiac hypertrophy provides important insights into the links between the mitochondrial ribosomal translational machinery and normal cardiac function." (PMID 36949106, 2023).
cardiomyopathy (2 papers, 2023 to 2024). A disease of the heart muscle or myocardium proper. "To characterize the expression and function of Mrps5 in cardiomyopathy, we first examined its expression during cardiac remodeling under stress conditions." (PMID 36949106, 2023).
heart failure (2 papers, 2023 to 2024). Inability of the heart to pump blood at an adequate rate to meet tissue metabolic requirements. "This critical role for Mrps5 in cardiac metabolism and mitonuclear communication highlights its potential as a target for heart failure therapies." (PMID 36949106, 2023).
arrhythmogenic right ventricular cardiomyopathy (1 paper, 2023). "The enriched pathways based on the KEGG database indicated that cardiac disease associated pathways, including “hypertrophic cardiomyopathy (HCM), dilated cardiomyopathy (DCM) and arrhythmogenic right ventricular cardiomyopathy (ARVC)” were enriched in the Mrps5 mutant embryonic hearts." (PMID 36949106, 2023).
congenital hypothyroidism (1 paper, 2025). A thyroid hormone deficiency present from birth. "APP, DDB1, MRPS5, and MRPL33 are hub genes with low expression levels in congenital hypothyroidism (CH)." (PMID 41169358, 2025).
gastric cancer (1 paper, 2025). A primary or metastatic malignant neoplasm involving the stomach. "This suggests that the roles of MRPL39,MRPS5,and DAP3 in gastric cancer may be complex." (PMID 40371222, 2025).
hepatocellular carcinoma (1 paper, 2025). A malignant tumor that arises from hepatocytes. "Moreover, MRPS5 has been shown to play an important role in the metabolic reprogramming of hepatocellular carcinoma cells." (PMID 41044669, 2025). "Bioinformatic analysis indicated that MRPS5 is closely related to the function of mitochondrial complex I. Further experiments confirmed that MRPS5 promoted the production of NAD, enhanced the mitochondrial of hepatocellular carcinoma, and participated in energy regulation." (PMID 41044669, 2025).
Hyperglycemia (1 paper, 2025). An increased concentration of glucose in the blood. "The identified signature genes (RPS13, MRPS5, MRPL21, MRPL22, NDUFS3) not only unravel the molecular cascade linking maternal hyperglycemia to fetal vascular dysfunction but also offer tangible targets for diagnostic and therapeutic innovation." (PMID 40727584, 2025).
leprosy (1 paper, 2020). Leprosy is a chronic infectious disease affecting primarily the skin and peripheral nervous system. "We found that a rare missense variant in mitochondrial ribosomal protein S5 (MRPS5) (MIM: 611972) contributes to leprosy susceptibility in Chinese patients." (PMID 33362202, 2020). "We identified several families carrying the MRPS5 Tyr137Cys variant and this variant was enriched in leprosy families compared to sporadic leprosy cases which demonstrate the power of using multiplex leprosy families for variant discovery." (PMID 33362202, 2020). "Further studies are needed to validate the association in more independent populations and to functionally characterize the role of MRPS5 in potentiating the susceptibility to leprosy." (PMID 33362202, 2020). "In summary, we have uncovered a missense variant in MRPS5 that contributes to leprosy risk in Chinese patients." (PMID 33362202, 2020). "We provide genetic evidence and expression data suggesting that MRPS5 is a novel leprosy-associated gene which may play an important role in the pathogenesis of leprosy." (PMID 33362202, 2020). "We have provided genetic evidence to indicate MRPS5 as a susceptibility locus for leprosy." (PMID 33362202, 2020). "In the end, the association between MRPS5 rs200730619 and leprosy was well validated in 369 cases (36/333, carrier frequency 9.76%) and 270 controls (11/259, carrier frequency 4.07%) (Padjusted = 0.006, OR = 2.74, CI = 1.345–5.587) after removing the unsuccessfully sequenced samples." (PMID 33362202, 2020). "Here, we report a potential leprosy-associated variant in mitochondrial ribosomal protein S5 (MRPS5) by using whole exome sequencing performed on 28 individuals including 8 leprosy-affected families and the follow-up SNP genotyping of the candidate variant in case-control sample sets." (PMID 33362202, 2020). "However, why this leprosy risk allele of MRPS5 is specifically enriched in East Asian populations and how it contributes to the population risk for leprosy remain to be determined." (PMID 33362202, 2020). "Our results indicated that MRPS5 may be involved in leprosy pathogenesis." (PMID 33362202, 2020).
lymphoma (1 paper, 2016). A malignant (clonal) proliferation of B- lymphocytes or T- lymphocytes which involves the lymph nodes, bone marrow and/or extranodal sites. "Knockdown of Ptcd3 or other mitochondrial ribosomal proteins (Mrps5 or Mrps27) decreased both expression of mitochondrion-encoded proteins and respiration rates, and was detrimental to Myc-driven lymphomas." (PMID 27635472, 2016).
cancer (5 papers, 2018 to 2025). A tumor composed of atypical neoplastic, often pleomorphic cells that invade other tissues. "Mitochondrial ribosomal protein S5 (MRPS5) is required for the enhanced mitochondrial function of LCSCs and promotes cancer commencement and development." (PMID 31608282, 2019). "In contrast, deacetylation of MRPS5, which is localized in the mitochondria, promoted the function of mitochondrial complex-I and production of NAD, enhanced mitochondrial respiration, and regulated the energy metabolism of cancer cells." (PMID 41044669, 2025). "Unlike non-cancer stem cells (CSCs), the maintenance of stemness of hepatic CSCs largely depends on the enhanced mitochondrial function induced by mitochondrial ribosomal protein S5 (MRPS5)." (PMID 35912218, 2022).
tumor (3 papers, 2019 to 2023). "According to previous studies and the results achieved from survival analysis, it may be hypothesized that MRPS5 acts as a tumor suppressor gene in GC and may be assigned as a favorable prognostic gene in GC patients." (PMID 37037466, 2023).
infection (2 papers, 2020 to 2023). The state of being infected such as from the introduction of a foreign agent such as serum, vaccine, antigenic substance or organism. "Further studies are needed to determine if defective MRPS5 could lead to impairment of energy metabolism of host immune cells, which could further cause defect in clearing M. leprae and increase susceptibility to infection." (PMID 33362202, 2020). "Therefore, rs200730619 may be a potential loss-of-function variant, and the mutant MRPS5 might have decreased activity during physiological processes against infection." (PMID 33362202, 2020). "Nine weeks post Mrps5 ablation (2 weeks post AAV9 infection), the cardiac function of Mrps5cKO mice treated with the control AAV9-Luci virus significantly decreased compared to that of the Mrps5fl/fl mice." (PMID 36949106, 2023). "Finally, 14 weeks post Mrps5 ablation (7 weeks post AAV9 infection), only AAV9-Klf15 treatment continued to ameliorate the cardiac phenotype of Mrps5cKO mice." (PMID 36949106, 2023).
MRPS5 also shares sentences with these, for which no sentence is quoted: cardiac disease (1 paper); Diamond-Blackfan anemia (1); dilated cardiomyopathy (1); hearing loss (1); hypertrophic cardiomyopathy (1); muscular dystrophies (1); ovarian carcinoma (1).